INS (insulin)
Diseases named in the same sentence as INS in open-access papers (continued):
Sharing a sentence is not in itself a finding about the gene and the disease.
diabetes (continued). "Hepatic GLUT1 is an insulin-independent facilitated glucose transporter that is known to have a higher gene expression during diabetes and fasting state." (PMID 40431415, 2025). "Type 2 diabetes (T2DM), characterized by insulin resistance and impaired insulin secretion, accounts for over 90% of diabetes cases and imposes substantial economic burdens exceeding $1 trillion USD annually in healthcare expenditures." (PMID 40951419, 2025). "In diabetic models, strategies aimed at reducing oxidative stress have demonstrated an enhancement in insulin sensitivity, underscoring the necessity of addressing oxidative stress in the management of diabetes." (PMID 40862129, 2025). "In the diabetes group, 88.4% of the patients were treated with insulin therapy and 44.2% were treated with oral hypoglycemic agents." (PMID 40106491, 2025). "MO bioactive compounds, especially isothiocyanates, regulate lipid metabolism, reduce body weight, and enhance insulin sensitivity, crucial for managing obesity-related conditions like diabetes and cardiovascular diseases." (PMID 40149610, 2025). "The development of diabetes in the human body primarily impacts the production and proper use of insulin." (PMID 41373952, 2025). "Type 1 diabetes mellitus (T1DM) is a lifelong chronic disease caused by genetic susceptibility, pancreatic β‐cell damage resulting in absolute deficiency of insulin secretion, also known as insulin‐dependent diabetes mellitus." (PMID 40256125, 2025). "Diabetes mellitus (DM) arises from a combination of genetic and environmental factors, leading to insufficient insulin secretion, insulin resistance, and consequential metabolic disturbances in glucose, protein, fat, water, and electrolyte balance." (PMID 40076319, 2025). "Data showed that serum insulin and IGF-1 were significantly elevated in prostate cancer, highest being in prostate cancer with diabetes, and they had a positive association with prostate cancer Gleason score, grade, and high risk." (PMID 41367482, 2025). "IMP2 is a mechanistic player in diabetes, as inactivating polymorphisms in IMP2 can lead to decreased pancreatic insulin secretion." (PMID 40141058, 2025). "Amylin, another gut-related hormone (co-secreted with insulin), also suppresses appetite and glucagon; the amylin analog pramlintide is approved for diabetes, and longer-acting amylin or amylin-plus-peptide co-agonists are advancing in obesity pipelines." (PMID 40871736, 2025). "A Delphi Survey was undertaken among a wider group of Primary Care Diabetes Technology Network members in the United Kingdom, to understand prevalent attitudes to management of adults with T2D on insulin and using CGM in primary care." (PMID 39676327, 2025). "The observed metabolic profile aligns with characteristics of type 1 diabetes or insulin-dependent diabetes mellitus, where impaired pancreatic insulin release plays a central role." (PMID 41375645, 2025). "In recent years, there has been growing interest in the role of functional foods as adjunctive strategies for diabetes management, alongside conventional therapies such as insulin administration, oral hypoglycemic agents, and lifestyle modifications." (PMID 41007307, 2025). "This study aimed to assess patient-reported outcomes related to self-management adherence, QoL, diabetes-related stigma, glycemic control, and other clinical outcomes along with their determinants, in insulin-treated pediatric T1DM patients in Jordan." (PMID 40323910, 2025). "When diabetes occurs, the pancreas is unable to effectively produce or utilize insulin, leading to abnormally elevated blood glucose levels." (PMID 40422047, 2025). "Although diabetes currently has no cure, it can be effectively managed through lifestyle changes, insulin (INS) therapy, and oral antidiabetic drugs." (PMID 40235340, 2025).
diabetes (continued). "These policies significantly increased the utilization of insulin pumps among older adults, improving glycemic control and reducing diabetes-related complications." (PMID 41473654, 2025). "A fixed rate i.v. insulin infusion (FRIII) of short-acting soluble insulin is recommended for the management of certain diabetes-related emergencies including DKA, SGLT-2 inhibitor-induced euglycaemic ketoacidosis, and HHS." (PMID 40480914, 2025). "Diabetes is a disease that results from the failure of the pancreas to produce adequate insulin or when the body is unable to utilize the insulin efficiently." (PMID 40966223, 2025). "A good balance in relation to diet, physical activity, insulin, and plasma glucose levels is needed to experience freedom when living with diabetes." (PMID 40765113, 2025). "Nine original studies documented data on insulin therapy in pregnancies with concomitant monogenic diabetes." (PMID 40649834, 2025). "Compared with the insulin demand–adequacy method, the RAD method was more stable and consistent in evaluating the risk of incident AGT and diabetes." (PMID 39611962, 2025). "The pathway enables a multifaceted diabetes intervention by simultaneously improving insulin signaling (AMPK‐dependent), normalizing metabolic flux (SIRT1‐mediated), and restoring mitochondrial function (PGC‐1α‐driven)." (PMID 41268687, 2025). "We conducted a proteome analysis of plasma samples from 17 matched pairs of pediatric patients with T1D; one cohort with severe DKA and another with insulin-controlled diabetes." (PMID 39773407, 2025). "While the SQI used in this study is more invasive than oral or transcutaneous routes, this method has extensive data showing that it is well tolerated for long-term self-administration of insulin by persons with diabetes." (PMID 40258026, 2025). "On 21 March 2024, the Committee for Medicinal Products for Human Use (CHMP) of EMA adopted a positive opinion, recommending the granting of a marketing authorization for insulin Icodec, intended for the treatment of diabetes mellitus." (PMID 41012462, 2025). "Bariatric surgery patients experience sustained improvements in glycemic control, often requiring fewer diabetes medications, including insulin." (PMID 40895654, 2025). "As also mentioned in the introduction, increased ceramide levels have been reported in several conditions frequently accompanying obstructive sleep apnea, such as obesity, coronary artery disease, insulin resistance, diabetes, hypertension or heart failure." (PMID 40970184, 2025). "The NLRP3 inflammasome serves as a redox‐sensitive hub in all three contexts: promoting tumor metastasis via IL‐1β, impairing insulin signaling in diabetes, and breaking immune tolerance in lupus." (PMID 40599237, 2025). "Type 2 diabetes mellitus (T2DM) is a chronic metabolic disorder primarily characterized by persistent hyperglycemia due to insulin resistance or inadequate insulin secretion." (PMID 40053775, 2025). "This inflammatory cascade results in aberrant insulin secretion from β cells, thereby contributing to the progression of diabetes." (PMID 40562805, 2025). "Diabetes is a long-term condition marked by either insufficient insulin production or resistance to insulin." (PMID 40006781, 2025). "As type 1 and type 2 diabetes manifest differences in insulin secretion, C-peptide can aid in distinguishing between diabetes types, helping to avoid misclassification." (PMID 40093566, 2025). "Diabetes mellitus is a common endocrine disorder in dogs and cats, and achieving stabilization with insulin alone can be challenging." (PMID 41472082, 2025). "The intricate molecular mechanisms elucidated in several studies highlight the versatility of anthocyanins in targeting key aspects of diabetes pathophysiology, ranging from carbohydrate metabolism and insulin resistance to inflammation and oxidative stress." (PMID 39136514, 2025).
diabetes (continued). "Diabetes is a metabolic disease characterized by hyperglycemia, which results from either defects in insulin secretion (type 1 diabetes) or insulin resistance, where insulin is produced but cannot effectively interact with its receptors (type 2 diabetes)." (PMID 40002348, 2025). "While several studies have examined the impact of the COVID-19 pandemic on diabetes care broadly, few have focused specifically on insulin management within safety-net primary care settings." (PMID 40700264, 2025). "The plant‐based, high‐fiber EAT‐Lancet diet supports weight control, lower obesity rates, glycemic control, and insulin sensitivity, which are critical in diabetes management." (PMID 40688606, 2025). "After multivariate adjustment (age, sex, duration of diabetes, glycaemic control, control of blood pressure, insulin, smoking, drinking, AVR, and PAVR), PA was a protective factor against moderate and severe NPDR." (PMID 41343177, 2025). "The findings revealed that both HIIT and TRF significantly improved FBG levels and insulin sensitivity in the T2D-induced rats compared to the diabetes-untreated control (D group)." (PMID 40362714, 2025). "Intraportal islet autotransplantation (IAT) simultaneous to TP is a potential option to prevent or alleviate pancreoprivic diabetes through partial preservation of endogenous insulin secretion." (PMID 40720532, 2025). "The participants who received training from the diabetes educator have a high frequency of expiry date checking habits (33%), and among them, 31% brought the insulin injection to room temperature before injection." (PMID 40376558, 2025). "Baseline characteristics were generally balanced across fidelity quartiles for clinical factors (age, sex, diabetes duration, insulin use, BMI, and comorbidity; all p > 0.05) but differed significantly for socioeconomic factors." (PMID 41048287, 2025). "Incorporating foods like BGNF, which are rich in fiber, helps improve insulin sensitivity and reduce the overall need for insulin, simplifying diabetes management." (PMID 40026940, 2025). "Some PwT2D were illiterate, had difficulty understanding diabetes and medications, hence they felt fearful and “helpless” about starting insulin." (PMID 40171977, 2025). "Previous research has established a link between insulin and OA, highlighting that conditions such as diabetes and metabolic syndrome alter the secretion of insulin and glucagon." (PMID 40538811, 2025). "Diabetes mellitus is a chronic metabolic disorder characterized by impaired insulin secretion or insulin resistance, resulting in elevated blood glucose levels." (PMID 40471961, 2025). "CGMs in combination with information and education gave novel insights into how the action of insulin can be influenced by the individual’s choices and actions, thus promoting useful actions to achieve improved diabetes self-management." (PMID 40116013, 2025). "Diabetic patients in these countries benefit from years of insulin independence, a functional cure for diabetes, and prolonged survival compared to those who remain dependent on insulin." (PMID 39949592, 2025). "People with T1D manage their diabetes either with a pen or a pump to deliver insulin as well as a technology to monitor their blood glucose." (PMID 39997249, 2025). "In the group of patients with diabetes, two patients were treated with metformin, while one patient was treated with metformin and insulin." (PMID 41244055, 2025). "His medical history included type 2 diabetes mellitus requiring insulin therapy, arterial hypertension, and benign prostatic hyperplasia." (PMID 41328084, 2025). "In both healthy and individuals with pre-diabetes, plasma glucose clearance is more efficient in the morning compared to the evening following similar glucose intake, as insulin sensitivity decreases later in the day." (PMID 39856244, 2025).
diabetes (continued). "Chronic inflammation is one of the characteristics of diabetes, which can lead to IR, impaired insulin secretion, and abnormal glucose tolerance." (PMID 40647154, 2025). "When these β-like cells were transplanted in vivo into mice with induced diabetes, they demonstrated glucose-dependent insulin secretion capable of fully compensating for the animals’ hormonal deficiency." (PMID 40943666, 2025). "The best‐fitting model, determined by the AIC and Schwarz's criterion (BIC), included the variables age, sex, diabetes duration, prior HbA1c, annual net income per person, daily insulin dose, and the interaction of HbA1c with sex." (PMID 39718005, 2025). "For example, extracts given as supplements to people with diabetes reduced blood glucose values significantly, increased insulin sensitivity, and improved glycemic management in clinical studies." (PMID 40842670, 2025). "Studies showed that reinforcement learning has been utilized to develop dynamic treatment regimens and provide a precise insulin dosage to react to the immediate needs of patients with diabetes, where the inspiration can be borrowed from PCOS management." (PMID 40549330, 2025). "Blood glucose levels are the primary marker for diabetes, directly influenced by the body’s ability to produce and utilize insulin." (PMID 40742490, 2025). "Diabetes mellitus (DM) represents a metabolic disorder characterized by inappropriately elevated blood glucose levels (BGL) resulting from either insulin deficiency or the body's inability to use insulin." (PMID 40432987, 2025). "Specifically, miR-223 is known to downregulate GLUT4 expression, which inhibits insulin-stimulated glucose uptake in adipocytes, suggesting its involvement in insulin resistance-related diseases such as type 2 diabetes mellitus (T2DM) and obesity." (PMID 41411269, 2025). "Diabetes mellitus is a chronic metabolic disorder characterized by persistent hyperglycemia, resulting from either insulin resistance or impaired insulin secretion." (PMID 40244271, 2025). "Such glucose-responsive insulin delivery systems can automatically release insulin according to blood glucose levels, which is crucial for effectively managing diabetes." (PMID 40421658, 2025). "Type 1 diabetes mellitus (T1DM) is a chronic autoimmune disease characterized by absolute insulin deficiency, requiring insulin therapy to maintain glycemic control and prevent disease complications." (PMID 41464725, 2025). "More research is needed to comprehend how β-cell insulin signaling impacts diabetes in bigger sample sizes." (PMID 40141412, 2025). "Other symptoms of hypoglycaemia such as nausea, falls or unsteadiness were reported in primary care in older people with diabetes treated with insulin who had a previous history of hypoglycaemia." (PMID 40863223, 2025). "Mutant mFicDR371S/R371S mice exhibit signature markers for syndromic diabetes including glucose intolerance and reduced serum insulin levels." (PMID 40073934, 2025). "Contemporary diabetes research focuses on leveraging the endocrine system’s natural physiology to develop therapies that closely mimic physiological insulin secretion." (PMID 40943666, 2025). "Phenylboronic acid-crosslinked HMNs offered glucose-sensitive swelling, ensuring self-regulated insulin delivery for diabetes management." (PMID 40136911, 2025). "The initial model included sex, puberty, diabetes duration, most recent HbA1c, BMI, height, daily insulin dose, systolic and diastolic blood pressure and CGM-derived metrics investigated as independent variables." (PMID 40414873, 2025). "Collectively, insulin-deficient type 2 diabetes and prediabetes subtypes (SIDD, MIDD, and IDPD) accounted for 80.1% of diabetes-related deaths, contributing disproportionately to premature mortality." (PMID 40678231, 2025).
diabetes (continued). "While we attempted to control the results for the main diabetes-related medications such as insulin, and metformin, as well as for wound care interventions like debridement, shoe and sock status, offloading, we did not control for all medications." (PMID 40498699, 2025). "The development of natural polymer-based insulin delivery systems represents a promising frontier in diabetes treatment, offering solutions that address both the efficacy and convenience of insulin therapy." (PMID 40352348, 2025). "Type 2 diabetes mellitus (T2DM) is a chronic metabolic disease primarily caused by two main factors: defective insulin secretion by pancreatic β-cells and the inability of insulin-sensitive tissues to respond to insulin." (PMID 41426839, 2025). "Streptozotocin (STZ) is widely used in diabetes research as it selectively destroys the insulin-producing β-cells in pancreatic islets, thereby inducing diabetes." (PMID 40002361, 2025). "They should also have experienced at least one severe hypoglycemic episode in the past year and suffer from impaired awareness of hypoglycemia despite ongoing insulin therapy, intensive diabetes management, and education." (PMID 40124184, 2025). "Current diabetes management involves regular blood glucose monitoring, lifestyle modifications, and pharmacological interventions, including insulin therapy and oral hypoglycemic agents." (PMID 40742490, 2025). "There were significant differences between patients and controls in terms of variables at the time of diagnosis of diabetes; BMI, physical activity, insulin level, FBS, TC, TG, LDL‐C, and creatinine levels (p < 0.05)." (PMID 40041714, 2025). "Insulin-requiring diabetes that responds poorly to sulfonylureas, most patients ultimately require insulin." (PMID 41465172, 2025). "Given ADPN’s role in enhancing insulin sensitivity, its specific contribution to corneal nerve repair in diabetes warrants deeper investigation." (PMID 41146365, 2025). "“Insulin self-titration” is a strategy where people living with diabetes adjust their insulin doses within parameters recommended by their diabetes care team." (PMID 41313169, 2025). "The study included incident cases of T1D identified by at least 2 diagnosis codes with at least 2 insulin prescriptions within 1 year and T2D identified by at least 2 diagnosis codes with at least 2 prescriptions of diabetes medication within 1 year." (PMID 39652325, 2025). "Instead, the patient's anti-glutamate decarboxylase levels reverted to normal, insulin production capacity improved, and classification as type 2 diabetes mellitus was ultimately reaffirmed." (PMID 40351955, 2025). "In the early stages of diabetes, specifically during the insulin resistance phase, inadequate insulin secretion or diminished sensitivity in the patient’s body hinders effective glucose utilization, leading to increased fat synthesis and subsequent obesity." (PMID 39761309, 2025). "The evaluation of endogenous insulin secretory capacity is important in the selection of diabetes treatment." (PMID 40820210, 2025). "Haemochromatosis patients with diabetes exhibited further declines in acute insulin response to glucose and insulin resistance." (PMID 40871742, 2025). "The development of an impulsive automated insulin delivery system (i-AiDS) for type 1 diabetes mellitus aims to provide real-time blood glucose regulation with minimal human intervention." (PMID 40906706, 2025). "By critically contextualizing our results within existing high-impact literature, this study strengthens the evidence for non-insulin-treated diabetes and hypothyroidism as independent—and potentially synergistic—drivers of DCM." (PMID 41153651, 2025). "Understanding its role in insulin signaling is crucial for developing new therapeutic approaches for diabetes and metabolic diseases." (PMID 40747301, 2025).